MECR (mitochondrial trans-2-enoyl-CoA reductase)
Description:
Catalyzes the NADPH-dependent reduction of trans-2-enoyl thioesters in mitochondrial fatty acid synthesis (fatty acid synthesis type II). Fatty acid chain elongation in mitochondria uses acyl carrier protein (ACP) as an acyl group carrier, but the enzyme accepts both ACP and CoA thioesters as substrates in vitro. Displays a preference for medium-chain over short- and long-chain substrates. May provide the octanoyl chain used for lipoic acid biosynthesis, regulating protein lipoylation and mitochondrial respiratory activity particularly in Purkinje cells (By similarity). Involved in iron homeostasis; affecting Fe-S cluster assembly and ceramide metabolism. Required for proper morphology and bioenergetic functions of mitochondria. Required for maintenance of neurons (By similarity).
Synonyms: CGI-63; NRBF1; FASN2B; ETR1; DYTOABG; OPA16
Tractability: Small molecule: it has a high-quality binding pocket. PROTAC: ubiquitination databases record sites on it; its protein half-life has been measured.
Gene: Protein-coding gene on chromosome 1 (29,192,657 to 29,230,945, reverse strand). Ensembl gene ENSG00000116353.
Subcellular location: Mitochondrion (Isoform 1); Cytoplasm (Isoform 2); Nucleus
Subcellular location (Human Protein Atlas): Mitochondria
Pathways (Reactome):
Metabolism: Beta oxidation of decanoyl-CoA to octanoyl-CoA-CoA
Gene Ontology:
Molecular function: enoyl-[acyl-carrier-protein] reductase (NADPH) activity; oxidoreductase activity
Biological process: ceramide biosynthetic process; fatty acid metabolic process; intracellular iron ion homeostasis
Cellular component: mitochondrion; mitochondrial matrix; cytoplasm; nucleus
Genetic constraint (gnomAD): Loss-of-function variants: 34 observed, 47.1 expected, observed/expected ratio (o/e) 0.72, 90% interval 0.55 to 0.96. The upper end of that interval is the gene's LOEUF score, 0.96, which puts it in group 4 of 6, group 1 being the genes least tolerant of losing a copy. Missense variants: 441 observed, 466.46 expected, observed/expected ratio (o/e) 0.95, 90% interval 0.87 to 1.02. Synonymous variants: 186 observed, 186.55 expected, observed/expected ratio (o/e) 1, 90% interval 0.88 to 1.13.
Gene-disease validity (ClinGen):
ClinGen rates the evidence that MECR causes each of these diseases.
Leigh syndrome (autosomal recessive): Moderate. A progressive neurological disease defined by specific neuropathological features associating brainstem and basal ganglia lesions.
Homologues: Orthologues: macaque MECR (98% identical), pig MECR (87% identical), dog MECR (85% identical), guinea pig MECR (84% identical), mouse Mecr (82% identical), rat Mecr (82% identical), rabbit MECR (80% identical), chimpanzee MECR (79% identical), tropical clawed frog mecr (59% identical), zebrafish mecr (59% identical), Drosophila melanogaster CG16935 (44% identical), Caenorhabditis elegans mecr-1 (41% identical). Paralogues in human: VAT1 (24% identical), RTN4IP1 (23% identical), TP53I3 (21% identical), VAT1L (21% identical), ADH5 (20% identical), ADH1C (20% identical), PTGR3 (20% identical), ADH1B (20% identical), CRYZ (20% identical), ADH1A (20% identical), ADH4 (18% identical), PTGR1 (18% identical), and 5 more.
Diseases named in the same sentence as MECR in open-access papers:
MECR is named in the same sentence as 24 diseases in open-access papers, as found by Europe PMC text mining. Sharing a sentence is not in itself a finding about the gene and the disease. The quoted sentences say what the papers report.
optic atrophy (6 papers, 2018 to 2025). A disorder characterized by loss of optic nerve fibers. "Mutations in human MECR cause severe neurodegeneration, often manifesting as childhood-onset dystonia, basal ganglia degeneration, and optic atrophy, collectively referred to as mitochondrial enoyl-CoA reductase protein-associated neurodegeneration (MEPAN)." (PMID 39859268, 2025). "It was recently reported that mitochondrial 2-enoyl-CoA/ACP reductase played an important role in placental development in mice and the mutations of MECR resulted in childhood-onset dystonia and optic atrophy." (PMID 29686696, 2018). "Although no information on the functional impacts of the MECR gene exists in dogs to date, in our 3 dogs, clinical signs and radiological findings share striking similarities with those reported in people with MECR variants and childhood‐onset dystonia and optic atrophy." (PMID 38041431, 2024). "One work found mutations in MECR (mitochondrial trans-2-enoyl-coenzyme A-reductase), which is involved in human mtFAS, in seven individuals who presented with childhood-onset dystonia and optic atrophy." (PMID 36551313, 2022). "Moreover, MECR is reportedly crucial in many diseases, such as hepatocelluar carcinoma, childhood-onset dystonia and optic atrophy." (PMID 34603851, 2021).
Dystonia (3 papers, 2018 to 2024). An abnormally increased muscular tone that causes fixed abnormal postures. "Additionally, MECR mutations cause a mitochondrial fatty-acid synthesis disorder and is characterized by a childhood-onset dystonia." (PMID 33255407, 2020).
Parkinson disease (2 papers, 2009 to 2025). A progressive degenerative disorder of the central nervous system characterized by loss of dopamine producing neurons in the substantia nigra and the presence of Lewy bodies in the substantia nigra and locus coeruleus. "For example, a search for Parkinson disease returns 12 mitochondrial DG with interactions to 24 predicted DG (e.g. CCS, MECR, PRKAR2B)." (PMID 19390613, 2009).
colitis (1 paper, 2025). Inflammation of the colon. "MECR deficiency decreased T cell fitness and led to reduced inflammation and disease severity in an inflammatory bowel disease (IBD) model of colitis." (PMID 40204636, 2025).
dyslipidemia (1 paper, 2020). "Some of the DE proteins predicted to affect mitochondrial function also cause dyslipidemia, including MECR, CS, ACLY, AOX3, and COX6B1 by RIS, and CYCS, COX6B1, and ENO3 by OLAN." (PMID 33302598, 2020).
endothelial dysfunction (1 paper, 2025). In vascular diseases, endothelial dysfunction is a systemic pathological state of the endothelium (the inner lining of blood vessels) and can be broadly defined as an imbalance between vasodilating and vasoconstricting substances produced by (or acting on) the endothelium. "The up-regulation of OXSM and MECR levels disrupts the “synthesis-degradation” balance of fatty acids, while Edu improves endothelial dysfunction, inhibits vascular wall inflammation and maintains vascular structural homeostasis by restoring this balance." (PMID 41614751, 2025).
Hypertension (1 paper, 2025). The presence of chronic increased pressure in the systemic arterial system. "Therefore, the functional status of OXSM and MECR largely determines the “synthesis-degradation” balance of fatty acid metabolism, thereby participating in the regulation of the pathological processes associated with vascular and target organ damage in hypertension." (PMID 41614751, 2025).
inflammatory bowel disease (1 paper, 2025). A spectrum of small and large bowel inflammatory diseases of unknown etiology. "Importantly, MECR-deficient T cells exhibited fitness disadvantages and were less effective at driving disease in an in vivo model of inflammatory bowel disease." (PMID 40204636, 2025).
influenza (1 paper, 2022). An acute viral infection of the respiratory tract, occurring in isolated cases, in epidemics, or in pandemics; it is caused by serologically different strains of viruses (influenzaviruses) designated A, B, and C, has a 3-day incubation period, and usually lasts for 3 to 10 days. "Phylogenetic analysis revealed that both MECR and the M77 that initiates cMECR are highly conserved in typical influenza hosts, including humans, birds, pigs, and horses." (PMID 36542656, 2022). "The genetic complementation approach also demonstrated that the anti-influenza activity of cMECR does not require the presence of full-length MECR, which is important considering MECR is known to homodimerize." (PMID 36542656, 2022).
Insulin resistance (1 paper, 2020). Increased resistance towards insulin, that is, diminished effectiveness of insulin in reducing blood glucose levels. "The data suggest that MECR protein is regulated in hepatocytes by ATP in association with insulin resistance." (PMID 32440681, 2020). "The MECR protein reduction was associated with insulin resistance and the protein restoration was associated with improvement of insulin sensitivity by BBR in the DIO mice." (PMID 32440681, 2020). "It is interesting to observe the association of MECR protein reduction and insulin resistance above." (PMID 32440681, 2020). "In the present study, we investigated mRNA and protein expression of MECR in diet-induced obese (DIO) mice in the study of insulin resistance." (PMID 32440681, 2020). "The study provides evidence for a relationship between MECR protein and insulin resistance." (PMID 32440681, 2020). "The observation suggests that MECR protein recover when the insulin resistance is corrected." (PMID 32440681, 2020). "Current study suggests that MECR may mediate the ATP signal in the DIO mice for insulin resistance." (PMID 32440681, 2020).
optic atrophy 15 (1 paper, 2024). "Mutations in lipid metabolism-related genes, including malonyl CoA:ACP acyltransferase (MCAT) and mitochondrial trans-2-enoyl-CoA reductase (MECR), are responsible for autosomal recessive optic atrophy 16 (OPA15) and optic atrophy 15 (OPA16), respectively." (PMID 39201313, 2024).
type 2 diabetes (1 paper, 2020). "MECR activity remains unknown in the mechanism of insulin resistance in the pathogenesis of type 2 diabetes." (PMID 32440681, 2020).
neurologic disorder (2 papers, 2023 to 2025). "MECR catalyzes the last step in mitochondrial fatty acid synthesis (mtFASII), and the mechanism by which loss of mtFASII leads to neurological disease is unknown." (PMID 41021813, 2025).
cancer (1 paper, 2023). A tumor composed of atypical neoplastic, often pleomorphic cells that invade other tissues. "Overlap of essential E‐boxes for four cancer cell lines revealed only three (1%) common E‐boxes: chr1_BS1363_CACAATG with neighbor genes MECR and PTPRU, chr11_BS79_CGCGTG localized near RPLP2 and PIDD1, and chr18_BS691_CATGTG adjacent to RBFA and TXNL4A." (PMID 37519063, 2023).
infection (1 paper, 2022). The state of being infected such as from the introduction of a foreign agent such as serum, vaccine, antigenic substance or organism. "Infection did not change the interactions; cMECR, but not MECR, interacted with the viral polymerase." (PMID 36542656, 2022). "Knockdown of MECR again increased infection by WSN, but not CA04." (PMID 36542656, 2022).
MECR also shares sentences with these, for which no sentence is quoted: Neurodegeneration (2 papers); fatty acid metabolism disorders (1); Huntington disease (1); Obesity (1); prion disease (1); retinal degeneration (1); spinocerebellar ataxia (1); tumor (1); viral infection (1).